MMP9 (matrix metallopeptidase 9)
Diseases named in the same sentence as MMP9 in open-access papers (continued):
Sharing a sentence is not in itself a finding about the gene and the disease.
osteoarthritis (69 papers, 2006 to 2025). A noninflammatory degenerative joint disease occurring chiefly in older persons, characterized by degeneration of the articular cartilage, hypertrophy of bone at the margins and changes in the synovial membrane. "Expression of gelatinases such as MMP-2 (gelatinase A) and MMP-9 (gelatinase B) has been shown to associate with the pathogenesis of osteoarthritis." (PMID 32189997, 2020). "In the pathophysiology of osteoarthritis, collagenases trigger the degradation of type II collagen, after which the resulting fragments become susceptible to degradation by other enzymes, such as gelatinase MMP-9." (PMID 39582715, 2024). "Peng Teng demonstrated that stimulation of α7nAChR by nicotine attenuated monosodium iodoacetate-induced cartilage degradation and osteoarthritis pain, this protective effect of nicotine is associated with the inhibition of MMP-9 overexpression via the PI3K/Akt/NF-kB signaling pathway." (PMID 35812436, 2022). "Spatially upregulated genes that overlap between SZ and HZ included an inhibitor of angiogenesis Adamts1, as well as matrix metalloproteinases Mmp9 and Mmp13, which are essential for endochondral bone formation but also implicated in the pathophysiology of osteoarthritis." (PMID 25068449, 2014). "Recent studies have shown that MMP-2 and MMP-9 are expressed in patients with RA and osteoarthritis, contributing to the progression of structural joint changes; MMP-9 specifically is associated with inflammation and degradation of the cartilage." (PMID 40278388, 2025). "A strong positive correlation between Mmp9 and shed Sdc4 has been identified in the synovial fluid of osteoarthritis patients, while inhibition or knockdown of Mmp9 reduces Sdc4 shedding." (PMID 40180176, 2025). "In osteoarthritis, a chorionic inflammatory disease, elevated MMP-9 levels correlate with cartilage degradation and disease progression." (PMID 40244002, 2025). "In conclusion, inhibiting IL-33 can significantly lower inflammatory factor levels in the knee joint, including IL-33 and MMP-9, and it can improve cartilage breakdown in osteoarthritis of the knee." (PMID 39172956, 2024). "Taken together, the MMP-9 ELISA used in this study provides the best reliable results previously confirmed by the zymography analysis of synovial fluids from horses with degenerative joint disease." (PMID 38136813, 2023). "The MMP-9 level in the plasma and synovial fluid of patients with RA is higher than this enzyme’s level in patients with osteoarthritis." (PMID 36676791, 2023). "Firstly, the study aimed to compare the level of MMP-9 in plasma (PL) and synovial fluid (SF) of patients with RA and osteoarthritis (OA)." (PMID 36676791, 2023). "Similar to our results, a group of Japanese authors suggested a significantly higher level of MMP-9 in the synovial fluid of RA patients compared to people with osteoarthritis." (PMID 36676791, 2023). "According to our results, MMP-9 level is higher in patients with RA than in patients with osteoarthritis, both in plasma (19.26 ± 7.54 vs. 14.57 ± 3.11 ng/mL) and synovial fluid (16.17 ± 12.25 vs. 0.75 ± 0.53 ng/mL)." (PMID 36676791, 2023). "All osteoarthritis parameters including IL-1β, caspase 3 and MMP-9 were significantly increased in the obese group compared to control." (PMID 36097281, 2022). "Significant reductions in the serum levels of MMP-2 and MMP-9 indicate that JBT has a role to play in preventing osteoarthritis." (PMID 36062127, 2022). "The same study revealed that oral administration of sesamol (30 mg/kg, p.o.)for 2 weeks attenuated MMP-1 and MMP-9 expression in the cartilage of monosodium iodoacetate (MIA)-induced osteoarthritis in male Wistar rats." (PMID 34760018, 2021). "Matrix metalloproteinase-9 (MMP-9) is a matrix metalloprotein capable of inducingchondrocyte damage through osteoarthritis and collagen degradation and canfacilitate angiogenesis in osteoarthritis tissues that induce pannus." (PMID 31778526, 2019).
osteoarthritis (continued). "MMP-9 has been shown to digest ECM and to cleave products of collagen type I and II proteolysis often associated with osteoarthritis." (PMID 26877866, 2016). "RT-PCR showed that the expressions of CD147, MMP-2 and MMP-9 mRNA was higher in RA FLS than in osteoarthritis FLS." (PMID 16507143, 2006). "MMP-9 (gelatinase B), which is uniquely secreted by osteoclasts into resorption lacunae to degrade type IV collagen and denatured collagens, shows elevated expression levels correlating with osteoarthritis severity." (PMID 40244002, 2025). "Furthermore, others have shown in a mouse model of osteoarthritis and in LPS-stimulated bone-marrow-derived macrophages that nicotine treatment in a concentration like ours (1.0 mg/kg) can reduce MMP9." (PMID 37239088, 2023). "Moreover, GSK-J4 suppressed the IL-1β-mediated increase in the expression of the cartilage-degrading matrix metalloproteinases 9 (MMP9) and 13 (MMP13) and ADAMTS5 in HACs and, therefore, has the potential to attenuate cartilage loss in osteoarthritis patients." (PMID 35915507, 2022). "However, in the articular cartilage, MMP-2 and MMP-9 have been studied in osteoarthritis (OA) and normal cartilage samples." (PMID 36278554, 2022). "MMP3 and MMP9 are upregulated in chondrocytes in osteoarthritis." (PMID 35164658, 2022). "In addition, similar patterns were observed in the serum MMP-9, a representative serum biomarker for osteoarthritis." (PMID 35269885, 2022). "Many proteolytic enzymes such as MMP-2, MMP-9, or cathepsin-K were involved in bone remodeling process, and MMPs were key degrading enzyme expressed in either physiological or pathological conditions including osteoarthritis, and osteoporosis." (PMID 32165922, 2020). "Besides, the study showed that CCL11 was able to stimulate the release of MMP-9 in synoviocytes from patients with osteoarthritis." (PMID 32189997, 2020). "Similarly, MMP-13, MMP-3, MMP-2, and MMP-9 increased in the cell line model of osteoarthritis." (PMID 32189997, 2020). "While FRZB, important in the progression of osteoarthritis, was decreased (FC = 0.26), mainly the inflammatory factors related to osteoarthritis such as IL1R (FC = 1.24), IL-1b (FC = 2.31), MMP9 and PTGS2 showed an increased expression after the intervention." (PMID 35159340, 2022). "Overexpression of ERRγ has been shown to increase the expression of matrix metalloproteinase (MMP9) and vascular endothelial growth factor A (VEGFA) in chondrocytes, resulting in extracellular matrix degradation and vascular proliferation in osteoarthritis." (PMID 35954227, 2022). "The expression levels of TCA1, TLR7, MMP9, CXCL10, CXCL13, HLA-DRA, and ADIPOQSPP1 were significantly higher in the IL-1β-induced group than in the osteoarthritis group in an in vitro qPCR experiment." (PMID 35734177, 2022). "We found the possible use of glucosamine, an antagonist of MMP9, in CTD-PAH, but most studies have focused on its clinical use in patients with osteoarthritis thus far." (PMID 35370713, 2022). "A disintegrin and metalloproteinase with thrombospondin motifs 5 (ADAMTS-5) and matrix metalloproteinases-9 (MMP-9) are degradative enzymes that exhibit proteolytic activity on ECM, hence promoting osteoarthritis development." (PMID 35684387, 2022). "A genome-wide analysis of DNA methylation status involving osteoarthritis patients found the MMP3, MMP9, and MMP13 genes to be hypomethylated (with increased gene expression) in osteoarthritis versus non-osteoarthritis chondrocytes." (PMID 33920915, 2021). "The percentage of methylated CpG sites of these MMP genes in clonal chondrocytes from osteoarthritis patients versus controls were: 80% versus 96% for MMP13, 19% versus 53% for MMP9, and 43% versus 70% for MMP3." (PMID 33920915, 2021). "MMP-3, MMP-9, and MMP-13 levels increased in animals induced with osteoarthritis, but the TIMP-2 level was shown to decline." (PMID 32189997, 2020).
osteoarthritis (continued). "Previous report has shown that increased MMP-1, MMP-3, MMP-9, MMP-12, and MMP-13, VEGF-A, and COL10A1, triggered by hypoxia-inducible factor (HIF)-2, play a vital role during osteoarthritis development." (PMID 31766662, 2019). "The predicted pathway also correlated the Histone Deacetylase 2 (HDCA2) with IL6 and MMP9 and RELA which was seem to be boost the progression of osteoarthritis by repressing cartilage specific gene." (PMID 29731966, 2018). "Effects of SAMC on MMP-9, MMP-13, and TIMP-1 protein expression in osteoarthritis chondrocytes were detected using western blot." (PMID 29333456, 2017). "The specific degradation of type II collagen and aggrecan by matrix metalloproteinase (MMP)-9, -13 and ADAMTS-4 and -5 (aggrecanase-1 and -2) in the cartilage matrix is a critical step in pathology of osteoarthritis (OA)." (PMID 25909781, 2015). "The genes enriched in the osteoarthritis pathway revealed by IPA of the DEGs in the palovarotene-treated chondrocytes included various matrix catabolic genes (Adamts4, Adamts5, Mmp9, Mmp10, Mmp12, and Mmp13) and cell death-related genes (Casp1, Casp3, and Casp6)." (PMID 39062860, 2024). "Additionally, ferulic acid, another HY-LL component, has been found to mitigate osteoarthritis chondrocyte toxicity by inhibiting the production of IL-6, PGE-2, and sub-MMP-9 and activating the SIRT1/AMPK/PGC-1α signaling pathway." (PMID 39337919, 2024). "Future research will focus on analyzing the protein expression of MMP-2, MMP-3, MMP-9, and MMP-13 to more fully elucidate the molecular mechanisms by which BSRE impacts osteoarthritis progression, providing valuable insights for developing more effective therapeutic strategies." (PMID 38542192, 2024). "Additionally, NO can be beneficial in the treatment of osteoarthritis by strongly inhibiting the expression of gelatinases like MMP-2 and MMP-9, which play a significant role in cartilage and bone destruction." (PMID 37623223, 2023). "Downregulated genes such as Postn and Mmp9 are negative indicators, and their increased expression promotes the progression of osteoarthritis." (PMID 37993861, 2023). "HIF-2α is involved in a pathway that promotes osteoarthritis degradation and regulates the expression of genes related to chondrocyte hypertrophy and differentiation, such as COL10A1 and RUNX2, and the expression of genes related to ECM degradation, such as MMP9, MMP13, MMP3, ADAMTS." (PMID 36503684, 2022). "In patients with severe osteoarthritis, dysregulation of OPN, MMP-9, and metalloproteinase with thrombospondin motifs 4 (ADAMTS-4) and a disintegrin was demonstrated to be important for the pathogenesis, suggesting that MMP-9 and thrombin are induced in osteoarthritis." (PMID 34440210, 2021). "MMP9 is widely expressed in noninfected normal connective tissues; it participates in the degradation of extracellular matrix, inflammatory response, and immune response and is related to the pathogenesis of osteoarthritis." (PMID 33376732, 2020).
triple-negative breast carcinoma (66 papers, 2014 to 2025). An invasive breast carcinoma which is negative for expression of estrogen receptor (ER), progesterone receptor (PR), and human epidermal growth factor receptor 2 (HER2). "Inhibited invasion, migration, and proliferation of triple-negative breast cancer cells by downregulating MMP-9 and CXCR4, implying use in treating invasive breast cancer." (PMID 40297577, 2025). "The fluorescence results demonstrated significant colocalization of p-JNK and MMP9 in triple-negative breast cancer, with significant inhibition of p-JNK and MMP9 expression after atorvastatin treatment." (PMID 38907234, 2024). "A combination of curcumin, berberine and quercetin was shown to effectively inhibit the expression of E-cadherin, mesenchymal N-cadherin, β-catenin, CD44 marker and MMP9 in triple-negative breast cancer cells." (PMID 36015440, 2022). "EZH2 inhibits the transcription of TIMP2, which boosts activities of MMP-2 and MMP-9, which in turn increases the invasive activity of triple-negative breast cancer cells." (PMID 35912155, 2022). "In KISS1R overexpressing triple-negative breast cancer (TNBC) cells, stimulation has been associated with increased invasion and MMP-9 expression, leading to the suggestion that hormone receptor status determines the metastatic effects of kisspeptin." (PMID 35955878, 2022). "Recent studies have also found that luteolin significantly inhibits cancer cell proliferation and metastasis through the AKT/mTOR/MMP9 signaling pathway in androgen receptor-positive triple-negative breast cancer." (PMID 35678671, 2022). "In conclusion, our study found that the up-regulation of SIPA1 can promote the expression of LINC01615, and the up-regulation of LINC01615 can promote the expression of MMP9 to promote the migration and invasion of triple-negative breast cancer." (PMID 36230738, 2022). "MMP-1 and MMP-9 are also very important in these processes, especially in cancers with different receptor profiles, e.g., progesterone positive (ER+) and triple-negative breast cancer (TNBC)." (PMID 34884588, 2021). "Inhibition of MLK3 downregulated the expression of FRA-1, MMP-1 and MMP-9, leading to the transendothelial migration and matrigel invasion of triple-negative breast cancer cells." (PMID 33407478, 2021). "This study aimed to investigate the clinical utility of serum and histological MMP-9 detection during neoadjuvant chemotherapy (NAC) for triple-negative breast cancer (TNBC)." (PMID 30241470, 2018). "Tumor cell-produced MMP9 promotes vessel formation in an orthotopic allograft model of basal-like triple negative breast cancer." (PMID 26674531, 2015). "Further studies will be needed to unravel the mechanisms by which tumor cell-produced MMP9 drives invasion and metastatic progression specifically in models of basal-like triple negative breast cancer." (PMID 24811362, 2014). "In this study, we have identified MMP9 expression by tumor cells themselves as a critical factor mediating the invasion and metastasis of basal-like triple negative breast cancers." (PMID 24811362, 2014). "This analysis confirmed the association between the high levels of MMP-9 expression (total scores >4) with tumors of high histological grade (Grade III) including both HER2-positive and triple-negative breast cancers." (PMID 25151367, 2014). "Ectoproteases may also aid in identifying and developing novel strategies for cancer treatment, including the difficult-to-treat triple-negative breast cancer through the inhibition of ADAM17 or MMP9." (PMID 35158891, 2022). "Similarly, co-expression of CD133, MMP2, and MMP9 was also observed in triple-negative breast cancer cells." (PMID 31623313, 2019). "MMP9 may offer a target for anti-metastatic therapies for basal-like triple negative breast cancers." (PMID 26674531, 2015). "In addition, MMP-9 levels are similar in triple negative breast cancer (TNBC) and in estrogen-dependent breast cancer." (PMID 24944618, 2014).
triple-negative breast carcinoma (continued). "Our results suggest that MMP9 may offer a target for anti-metastatic therapies for basal-like triple negative breast cancers, a poor prognosis subtype with few available molecularly targeted therapeutic options." (PMID 24811362, 2014). "Hence, our findings support the conclusions of recently published studies indicating a positive correlation between high levels of MMP-9 expression and triple-negative breast cancers." (PMID 25151367, 2014). "Hypothesizing that MMP9 may act as a general driver of the invasive/metastatic propensities of triple negative breast cancers, we evaluated the impact of MMP9 knockdown on basal-like, triple negative breast cancer cell lines BT-549 and SUM159PT." (PMID 24811362, 2014). "In in vitro experiments, by promoting the expression of cyt c, caspase-9 and caspase-3 and blocking the expression of matrix metalloproteinase 9 (MMP-9), it has a significant antimetastatic effect on triple-negative breast cancer (TNBC)." (PMID 41191140, 2025). "Baicalin inhibits the protein expression of MMP9, TNF-α and JAK2 and their related signaling pathways in the treatment of triple-negative breast cancer." (PMID 40356970, 2025). "In triple negative breast cancer cells (TNBC), we showed that ARF1 controlled mainly the activation of MMP9 and MMP2 through FAK37." (PMID 35680971, 2022). "In triple-negative breast cancer cell lines, pimozide inhibited the STAT-3 mediated activation of matrix metalloproteinase-9 (MMP-9) and vimentin, while in brain tumor cell lines, it induced a STAT-3 mediated apoptosis in vitro and in vivo." (PMID 34944601, 2021). "Further, we reported another mechanism by which IGF2BP3 knockdown reduced the MMP2 and MMP9 protein levels in OCCC, as shown in triple negative breast cancer before." (PMID 32083017, 2019). "Eugenol-treated cells showed significantly decreased MMP2 and MMP9 expression and an insignificant increase in TIMP1 expression in HER2 positive and triple negative breast cancer cells." (PMID 30518369, 2018). "To confirm these findings and identify the cellular sources and localization of MMP-9 within tumors, we assessed MMP-9 expression in gastric adenocarcinoma, CRC, and triple-negative breast cancer via immunohistochemistry (IHC)." (PMID 30500835, 2018). "The Py8119 tumors used in this study represent the highly invasive triple negative breast cancer that have elevated levels of MMP-2 and MMP-9 activity." (PMID 26336058, 2015). "Evidently, this sharply contrasts with the high levels of expression of MMP-9 found in the cytoplasm of both HER2-positive and triple-negative breast cancers cells." (PMID 25151367, 2014). "In contrast, high levels of MMP-9 expression were found in 87.9% of HER2-positive and 79.4% of triple-negative breast cancer when compared to normal (p < 0.001)." (PMID 25151367, 2014). "This list was further filtered through a triple-negative breast cancer (TNBC) scRNA-Seq dataset by applying a stringent criteria selection (i.e., high expression restricted to the macrophage cluster), leading to 4 genes: SPP1, APOC1, FCER1G, and MMP9." (PMID 39808498, 2025). "Similarly, in triple-negative breast cancer, piperine inhibited cell migration by downregulating the expression of MMP2 and MMP9." (PMID 36678600, 2023).
triple-negative breast carcinoma (continued). "In addition, MMP9 overexpression was correlated with unfavorable OS in patients with IDC (HR = 1.37, 95% CI 1.11–1.68, P = 0.003) and triple-negative breast cancer (TNBC) (HR = 1.88, 95% CI 1.39–2.55, P < 0.001)." (PMID 33568081, 2021). "In addition, treatment with 200 ng/ml CCL20 significantly enhanced cell invasion and stimulated the secretion of MMP-2 and MMP-9 in BT549 and HCC38 cell lines, which are basal-like/triple-negative breast cancer cell lines, as is the MDA-MB-231 cell line." (PMID 28851919, 2017). "Taken together, our results demonstrate that brucine inhibits the migration, invasion, and vasculogenic mimicry in human triple-negative breast cancer cell line MDA-MB-231, which might be through the disruption of cytoskeleton and downregulation of EphA2, MMP-9, and MMP-2." (PMID 30723742, 2019).